PAM16 (presequence translocase associated motor 16)
Description:
Regulates ATP-dependent protein translocation into the mitochondrial matrix. Inhibits DNAJC19 stimulation of HSPA9/Mortalin ATPase activity.
Synonyms: MAGMAS; TIM16; TIMM16; CGI-136; SMDMDM
Tractability: Antibody: UniProt places it where antibodies can reach, with high confidence. PROTAC: ubiquitination databases record sites on it; its protein half-life has been measured.
Gene: Protein-coding gene on chromosome 16 (4,331,549 to 4,355,607, reverse strand). Ensembl gene ENSG00000217930.
Subcellular location: Mitochondrion inner membrane
Subcellular location (Human Protein Atlas): Mitochondria; Nucleoplasm; Microtubules
Pathways (Reactome):
Protein localization: Mitochondrial protein import
Gene Ontology:
Molecular function: protein binding
Biological process: negative regulation of ATP-dependent activity; ossification; protein import into mitochondrial matrix; intracellular protein transport
Cellular component: matrix side of mitochondrial inner membrane; mitochondrial matrix; mitochondrion; PAM complex, Tim23 associated import motor; protein-containing complex; mitochondrial inner membrane; TIM23 mitochondrial import inner membrane translocase complex
Genetic constraint (gnomAD): Loss-of-function variants: 10 observed, 16.42 expected, observed/expected ratio (o/e) 0.61, 90% interval 0.38 to 1.03. The upper end of that interval is the gene's LOEUF score, 1.03, which puts it in group 4 of 6, group 1 being the genes least tolerant of losing a copy. Missense variants: 199 observed, 166.76 expected, observed/expected ratio (o/e) 1.19, 90% interval 1.06 to 1.34. Synonymous variants: 72 observed, 66.67 expected, observed/expected ratio (o/e) 1.08, 90% interval 0.89 to 1.31.
Homologues: Orthologues: mouse Pam16 (96% identical), mouse Pam16l (96% identical), rat Pam16 (94% identical), rabbit PAM16 (93% identical), guinea pig PAM16 (91% identical), tropical clawed frog pam16 (78% identical), zebrafish pam16 (77% identical), rat AABR07030524.1 (72% identical), Drosophila melanogaster blp (54% identical), Drosophila melanogaster CG1409 (49% identical), Caenorhabditis elegans F45G2.8 (42% identical).
Diseases named in the same sentence as PAM16 in open-access papers:
PAM16 is named in the same sentence as 17 diseases in open-access papers, as found by Europe PMC text mining. Sharing a sentence is not in itself a finding about the gene and the disease. The quoted sentences say what the papers report.
genetic diseases (1 paper, 2024). "Subunits implicated in genetic diseases include Timm50, Tim14 (DNAJC), Pam16 (Magmas), and mHsp70 (mortalin)." (PMID 39766801, 2024).
tumor (1 paper, 2025). "Lastly, PCa primary/local tumor samples with increased RNA expression of MAGMAS, gene alias PAM16, may predict decreased OS." (PMID 40361461, 2025).
PAM16 also shares sentences with these, for which no sentence is quoted: glioblastoma (3 papers); medulloblastoma (2); prostate carcinoma (2); ataxia syndrome (1); cancer (1); cardiac hypertrophy (1); cardiomyopathy (1); chondrodysplasia (1); dilated cardiomyopathy (1); glioma (1); heart failure (1); ovarian carcinoma (1); skeletal dysplasia (1); spondylodysplastic dysplasia (1); spondylometaphyseal dysplasia (1).